TLR4 (toll like receptor 4)
Diseases named in the same sentence as TLR4 in open-access papers (continued):
Sharing a sentence is not in itself a finding about the gene and the disease.
alcoholic liver diseases (32 papers, 2013 to 2026). A disorder caused by damage to the liver parenchyma due to alcohol consumption. "In summary, CA can prevent alcoholic liver disease by inhibiting the TLR4/MYD88/NF-κB pathway and regulating the gut microbiota." (PMID 41302431, 2025). "Studies have shown that GSB extract can ameliorate acute LI-induced necrosis, protect the liver, and alleviate alcoholic liver disease in mice via the modulation of the TLR4/NF-κB pathway." (PMID 41282626, 2025). "P-cresol glucuronide also plays an anti-inflammatory role mediated by TLR4, a key signaling pathway known to modulate immune response in both metabolic and alcoholic liver disease." (PMID 39335460, 2024). "Lactobacillus rhamnosus R0011 and Lactobacillus acidophilus R0052 reduced TLR4 expression in mice with alcoholic liver disease." (PMID 37138630, 2023). "In alcoholic liver disease, the gut microbiota and its components, including LPS and dsDNA, activate the TLR4/MyD88–ROS pathway in the portal circulation, thereby triggering NLRP6 inflammasome-mediated pyroptosis." (PMID 36969233, 2023). "In a study, oral administration of P. ginseng extracts to mice was shown to attenuate increased hepatic TLR4 expression in alcoholic liver disease." (PMID 37333474, 2023). "Large amounts of endotoxins translocated from the gut strongly activate Toll-like receptor 4 in the liver and play an important role in the progression of alcoholic liver disease (ALD), especially in severe alcoholic liver injury." (PMID 27682116, 2015). "The role of lipopolysaccharide (LPS) and toll-like receptor 4 (TLR 4) in the pathogenesis of alcoholic liver disease (ALD) has been widely established." (PMID 25692549, 2015). "The detoxification of the endotoxins from gram-negative bacteria releases a particular kind of endotoxin called LPS, which once in the liver, attaches to TLR4, and sets in action the pathway that leads to alcoholic liver disease." (PMID 24400890, 2014). "LPS signalling to TLR4 and its co-receptors stimulates Kupffer cells to release TNF-α, which causes scarring of liver tissue and ultimately alcoholic liver disease." (PMID 24400890, 2014). "Dietary CL inhibited the progression of alcoholic liver disease, and some of the possible mechanisms may be strengthening the intestinal barrier function, alleviating dysbiosis, and modulating the TLR4 pathway." (PMID 37483276, 2023). "Disruption of the gut microbiota and increased intestinal permeability can lead to the influx of endotoxins such as lipopolysaccharide (LPS) into the portal circulation, which activate toll-like receptor 4 (TLR4) to promote inflammation in alcoholic liver disease." (PMID 36960204, 2023). "Previous studies have reported the MyD-88 independent role of TLR-4 in alcoholic liver disease." (PMID 30057922, 2018). "Moreover, via a TLR4-mediated activation of Kupffer cells, fibrinogenesis is facilitated, and this could explain the diminished effect of G-CSF on patients with alcoholic liver disease." (PMID 37892679, 2023). "We found that 11 genes such as IL-6, TLR4, TNF, and CASP3 were interactive targets between GRg1 and ALD, suggesting that GRg1 protected alcoholic liver damage through these targets." (PMID 36052161, 2022). "The stimulation of Kupfer cells by LPS is mediated by LPS-specific toll-like receptor 4 (TLR4), which is involved in inflammatory response observed in alcoholic liver damage." (PMID 34836410, 2021). "In alcoholic liver disease (ALD), Tarangabin regulates the expression levels of tumor necrosis factor (TNF)-α and toll-like receptor 4 (TLR4) mRNA by acting on the lipopolysaccharide-TLR (LPS-TLR) signaling pathway, thereby improving the severity of ALD." (PMID 34721046, 2021). "Gut-derived LPS recruits macrophages via TLR4 to overexpress inflammatory cytokines such as IL-6, TNF-α, which contribute to the inflammatory processes in alcoholic liver disease." (PMID 31116255, 2019).
alcoholic liver diseases (continued). "In the liver, LPS leads to the activation of Kupffer cells, the liver resident macrophages, via stimulation of the Toll-like receptor 4 (TLR4) and the induction of an inflammatory response contributing to the progression of alcoholic liver disease." (PMID 30842741, 2019). "TLR4 is an attractive therapeutic target of CLD as it is involved in several hepatic inflammatory and fibrotic processes induced by various etiologies, such as NASH and alcoholic liver disease, as well as in animal models of chronic liver injury." (PMID 34205789, 2021). "Sera from alcoholic patients, but not from healthy controls, were able to stimulate TLR2- and TLR4-transfected HEK293 cells to secrete CXCL1, suggesting that CXCL1 up-regulation is dependent on soluble factors found in alcoholic liver disease, and involves TLR2 and TLR4 signaling." (PMID 24260493, 2013).
chronic obstructive pulmonary disease (32 papers, 2009 to 2025). A chronic and progressive lung disorder characterized by the loss of elasticity of the bronchial tree and the air sacs, destruction of the air sacs wall, thickening of the bronchial wall, and mucous accumulation in the bronchial tree. "Another pathophysiological condition associated with increased TLR4 activation is cardiac arrhythmias." (PMID 37239362, 2023). "Our results are in agreement with other previous studies that reported an association between TLR4 polymorphism with related‐disease chronic obstructive pulmonary disease in smokers." (PMID 31328431, 2019). "Recently, it was reported that cigarette smoke causing hypoxia reduced TLR4 mRNA and LPS responsiveness, and severe chronic obstructive pulmonary disease (COPD) had a more significant association with reduced TLR4 expression than less severe disease." (PMID 19960069, 2009). "Another LPS containing five acyl chains from the gut commensal Parabacteroides goldsteinii (lipid A moiety, 14) was deduced to alleviate chronic obstructive pulmonary disease (COPD) by inhibiting the TLR4 signaling pathway." (PMID 37013853, 2023). "We investigated whether single nucleotide polymorphisms (SNPs) in the TLR4 gene were associated with the emphysema phenotype in Japanese subjects with chronic obstructive pulmonary disease (COPD)." (PMID 22251849, 2012). "OBJECTIVE: Evaluate Bufei Decoction effects on chronic obstructive pulmonary disease (COPD) and elucidate Schisandrin B (Sch B) mechanism via TLR4 pathway." (PMID 41456077, 2025). "Studies have found that polydatin has a certain improvement effect on rats with chronic obstructive pulmonary disease, which may be related to inhibiting the Toll-Like Receptor 4 (TLR4) and Nuclear Factor kappa-light-chain-enhancer of activated B cells (NF-κB) signaling pathway." (PMID 40880648, 2025). "Previous reports have shown that in a chronic obstructive pulmonary disease (COPD) inflammatory model, SH attenuated inflammation by reducing the mRNA levels of TLR4, MyD88, and NF-κ B p65 and the protein expression of TLR4 and p65." (PMID 33716736, 2021). "There is mounting evidence that TLR4 triggers the initial lung inflammation in chronic obstructive pulmonary disease (COPD)." (PMID 33995400, 2021). "It was shown that activation of TLR4 decreased the action potential duration of cardiomyocytes via the IRF-3 pathway, a MyD88-independent pathway that leads to cardiac arrhythmias." (PMID 37239362, 2023). "The contribution of LPS and TLR4 signaling to disease pathology is often not clearly determined and can be positively or negatively associated with a disease as in the case of COPD (chronic obstructive pulmonary disease) and pulmonary fibrosis." (PMID 36678520, 2022). "Furthermore, AGER (which encodes RAGE) expression, rather than TLR4 expression, was significantly correlated with the sputum neutrophil count and airway hyper-responsiveness in patients with chronic obstructive pulmonary disease (COPD)." (PMID 35626330, 2022).
non-small cell lung carcinoma (31 papers, 2014 to 2025). A group of at least three distinct histological types of lung cancer, including non-small cell squamous cell carcinoma, adenocarcinoma, and large cell carcinoma. "The expression level of TLR4 is markedly linked to the histological type, clinical stage, and lymphatic infiltration in non-small cell lung cancer." (PMID 40860289, 2025). "Association between TLR4 and PD-L1 expression level and clinicopathologic variables in patients with non-small cell lung cancer." (PMID 28484456, 2017). "In the present study, we evaluated TLR4 expression and its association with programmed cell death ligand 1 (PD-L1) in non-small cell lung cancer (NSCLC) tissues and assessed the predicting value of TLR4 on postoperative outcome." (PMID 28484456, 2017). "Infection with the gram-negative E.Coli has been associated with tumor growth, progression and metastasis of non-small cell lung cancer, by promoting lipid synthesis through the TLR4/9 pathway and, also, by facilitating cancer stem cell properties through the TLR4/IL-33 pathway." (PMID 35366267, 2021). "In non-small cell lung cancer, the activation of TLR4 has been shown to promote the expression of PD-L1." (PMID 40999508, 2025). "Previous studies have demonstrated that expression levels of TLR4, 5, 7, 8, and 9 in non-small-cell lung carcinoma (NSCLC) are markedly higher than those in normal lung tissues." (PMID 37443143, 2023). "Reactive oxygen species (ROS) activate the signaling of TLR4 in non-small cell lung cancer (NSCLC) cells induced by lipopolysaccharide (LPS) stimulation." (PMID 34073777, 2021). "Carotenoid B triggered TLR4-induced pyroptosis via the GSDMD pathway in non-small cell lung cancer." (PMID 40756987, 2025). "Moreover TLR4, which is expressed in non-small cell lung cancer, is known to induce PD-L1 expression upon stimulation with E. coli LPS." (PMID 38254832, 2024). "A recent study found that serum TLR4 was elevated in Non-Small Cell Lung Cancer (NSCLC)." (PMID 38315263, 2024). "TLR4, TLR5, TLR7, and TLR8 were more highly expressed in non-small cell lung cancer (NSCLC)." (PMID 41471188, 2025).
diabetic retinopathy (30 papers, 2014 to 2026). "Reports of association between TLR4 polymorphism and diabetic retinopathy." (PMID 38983565, 2022). "Further studies on the association of miR-146a with TLR4 and MyD88 pathways will broaden our understanding on the regulation of retinal endothelial permeability and contribute to developing novel therapeutic strategies for the complications of diabetic retinopathy." (PMID 26997759, 2016). "In addition, TLR4 gene polymorphism was found to be associated with diabetic retinopathy." (PMID 26468333, 2015). "Phosphorylated IRF3 initiates signal transducer and activator of transcription 6 (STAT6) activation, amplifying IFN-β1 production, a process also observed in Toll-like receptor 4 (TLR4)-mediated blood–retinal barrier breakdown during diabetic retinopathy." (PMID 41487469, 2026). "In this in vitro study, they showed that BM-MSC-derived EVs can play a protective role in diabetic retinopathy via TLR4/NF-κB axis repression by upregulating miR-486-3p expression from high-glucose-treated Muller cells." (PMID 37240353, 2023). "Meanwhile, upregulating miR-486-3p or downregulating TLR4 inhibits diabetic retinopathy motivators such as oxidative stress, inflammation, and apoptosis." (PMID 37240353, 2023). "To verify the influence of the TLR4/NF-kB signaling pathway on inflammatory factors and growth factors in diabetic retinopathy, we used the TLR4/NF-kB signaling inhibitor TAK-242." (PMID 37819496, 2023). "TLR4 antagonists can efficiently block the inflammatory response in diseases such as corneal xenotransplantation and diabetic retinopathy." (PMID 36124139, 2022). "TLR4 gene Asp299Gly polymorphism was associated with increased risk of microvascular complications in patients with T2DM, especially diabetic retinopathy (DR)." (PMID 35672795, 2022). "Compared with wild-type diabetic mice, TLR4 knockout mice exhibited improvements in diabetic retinopathy due to inhibition of the NF-kB signaling pathway and downstream inflammation, as well as downregulation of the expression of VEGF and GFAP." (PMID 36124139, 2022). "Hsa-miR-145-5p was down-regulated in high glucose-treated retinal endothelial cells (a cellular model of diabetic retinopathy), and hsa-miR-145-5p overexpression significantly reduced TLR4 at both the protein and mRNA levels." (PMID 34149728, 2021). "Specially, grafting bone marrow‐derived cells from TLR4 wild‐type mice into TLR4 mutant mice increased the damage to the retina, which indicated an essential role for TLR4 in bone marrow‐derived cells contributing to the progression of diabetic retinopathy." (PMID 32902129, 2020). "Currently, studies about TLR4 polymorphisms in the ocular diseases were mainly focused on age-related macular degeneration (AMD), diabetic retinopathy (DR), and OAG." (PMID 31428642, 2019). "Gas is the main component of GEB, it inhibits high glucose-induced human retinal endothelial cell apoptosis by regulating the SITR1/TLR4/NF-κBp65 signaling pathway, indicating its protective effects on diabetic retinopathy." (PMID 30524286, 2018). "Use of the Müller cell specific conditional knockout mice will allow us to investigate the role of TLR4 in Müller cells in retinal I/R and diabetic retinopathy." (PMID 29287085, 2017). "Now that we have characterized these mice and shown TLR4 signaling in the retinal Müller cells, we will extend these studies into work on ischemia/reperfusion (I/R) and diabetic retinopathy models." (PMID 29287085, 2017). "Work in other retinal cells has shown that TLR4 in bone marrow derived cells is involved in the progression of diabetic retinopathy." (PMID 29287085, 2017). "In this study, we at first examined the expression of TLR4 in the premembranes of patients with diabetic retinopathy." (PMID 26468333, 2015). "Previous studies have also recognized HMOX1 and TLR4 as diabetic retinopathy biomarkers." (PMID 40282274, 2025). "TLR4 is one of many inflammatory pathways in diabetic retinopathy." (PMID 36124139, 2022).
diabetic retinopathy (continued). "Thus, our findings of increased TLR4 in endothelial cells after high glucose exposure provide the evidence for the role of TLR4 in diabetic retinopathy." (PMID 26468333, 2015). "However, the impact of TLR4 on the pathogenesis of diabetic retinopathy (DR) is poorly understood." (PMID 26468333, 2015). "Further analysis involving PPI network construction and multiple algorithms identified HMOX1, TLR4, and ACE as biomarkers of diabetic retinopathy." (PMID 40282274, 2025). "Although we have identified the critical roles of HMOX1, TLR4, and ACE in diabetic retinopathy through bioinformatics analysis and experimental validation, this study still has several limitations." (PMID 40282274, 2025). "In diabetic retinopathy, the NLRP3 inhibitor verapamil can significantly inhibit TLR4-mediated NLRP3 activation, reduce IL-1β and TNF-α levels and improve RGC survival." (PMID 39736512, 2024). "In this study, the key pyroptosis-related genes in diabetic retinopathy, such as CASP3, GBP2, and TLR4, were preliminarily identified by bioinformatics analysis and confirmed by GSE179568 and qRT-PCR in a diabetic model." (PMID 35957838, 2022). "Similarly, in diabetic retinopathy, PLT-Exo secretion is significantly increased and CXCL10 is upregulated, which activate the toll like receptor 4 (TLR4) signaling pathway and induce retinal endothelial injury." (PMID 35498048, 2022). "It attenuates diabetic retinopathy by alleviating retinal inflammation through upregulation of SOCS3 expression, suppression of toll-like receptor 4 (TLR4) signaling, and reduction of MMP-9 production, and of inflammatory factors including TLR4/p38/NF-κB signaling pathways in BV2 cells." (PMID 29937497, 2018).
neuropathy (30 papers, 2011 to 2025). A disorder affecting the nervous system that manifests with pain, tingling, numbness, and/or muscle weakness. "Summing up, in light of the interactions of Notch1 and TLR4 signaling pathways, both Notch1 and TLR4 signaling pathway may indeed play a significant role in development of neuropathy, which could be linked to the nociceptive behavior in diabetic neuropathy." (PMID 29097792, 2017). "What is more, TLR2 or TLR4 deficient animals with induced neuropathy are more resistant to pain." (PMID 26962463, 2016). "Summing up, in light of their upregulation over the course of pain, both TLR2 and TLR4 may indeed play a significant role in neuropathy, which could be linked to the observed activation of IBA-1/CD40-positive cells." (PMID 26962463, 2016). "It is suggested that the symptoms of neuropathy are a result of the interaction of paclitaxel with TLR-4 (toll-like receptor 4) on macrophages and the activation of a cascade of pro-inflammatory factors." (PMID 40149322, 2025). "Our results are in harmony with other studies which demonstrated the neuropathy of LPS through binding to TLR4, activation of NF-κB followed by the release of inflammatory cytokines, and ultimately taupathy and amyloid plaque deposition." (PMID 39063042, 2024). "Our results found an over-expression of TLR4 spinal levels on 14 (P < 0.05) and 21 (P < 0.01) days of neuropathy compared to control animals (vehicle-treated mice)." (PMID 38384464, 2024). "Our study is the first to investigate the therapeutic potential and mechanism of HBOT for PAC-induced neuropathy by using a TLR4 agonist and TLR4 antagonist intervention." (PMID 36982452, 2023). "TLR4 is also involved in innate neuroimmunity and neuropathy and mediates inflammatory and neuropathic pain." (PMID 33535986, 2021). "It was observed that the expression levels of TLR4 were increased in diabetic patients who developed neuropathy compared to those in healthy subjects and diabetic patients who did not develop neuropathy." (PMID 33669048, 2021). "In a study in rats, macrophages were stimulated with LPS in co-culture with DRG neurons, and this led to apoptosis of neurons, suggesting a role for TLR4 in neuropathy." (PMID 32854769, 2020). "Despite evidence of microglial activation in neuropathic females, microglial TLR4 signaling is only necessary for the development of neuropathy in males, whereas astrocytic signaling under neuropathic conditions is observed in both males and females." (PMID 31763376, 2019). "So, Microglial TLR4 plays a crucial part as a receptor in the induction phase of behavioral hypersensitivity in rodent models of neuropathy." (PMID 32641971, 2019). "LPS and endogenous ligands for TLR4, lead to NF-κB activation and subsequent induction of pro-inflammatory cytokines, which contribute to neuropathy pain process." (PMID 32641971, 2019). "TLR4 blockade has analgesic properties and restores the balance between nociceptive factors, which indicates its engagement in neuropathy development." (PMID 29656686, 2018). "In our opinion, a better understanding of the role of TLR4 signalling in injury-induced pain will facilitate the development of neuropathy treatment." (PMID 29656686, 2018). "Using behavioural/biochemical methods, we examined the influence of TLR4 antagonist on levels of hypersensitivity and nociceptive factors whose contribution to neuropathy development has been confirmed." (PMID 29656686, 2018). "In the CNS, TLR2, and TLR4 are predominantly expressed on glial cells, with the greatest importance in the context of neuropathy on microglia." (PMID 28491822, 2017). "This implies that the only change that can be observed in the DRG occurs at the beginning of neuropathy progression, so it can be assumed that the response of TLR4 to the injury state in the DRG is faster than that of TLR2." (PMID 26962463, 2016).